NF1 (neurofibromin 1)
Diseases named in the same sentence as NF1 in open-access papers (continued):
Sharing a sentence is not in itself a finding about the gene and the disease.
neurofibroma (continued). "We have developed an NF1 minipig that recapitulates the diverse phenotypes seen in NF1 patients, including the development of CALMs, neurofibromas, and OPG." (PMID 30302402, 2018). "Selumetinib has shown promising results in treating children with NF1 mutant plexiform neurofibromas, while PD-0325901 has shown efficacy in treating NF1 mutant neurofibromas in mouse- and human-derived malignant peripheral nerve sheath xenografts." (PMID 29617658, 2018). "Solitary neurofibromas in “clinically” non-NF-1 patients are benign tumors and the identification of genetic aberrations in these tumors are not expected to play a role in diagnosis." (PMID 29426349, 2018). "A top priority is to continue to gather large repositories of NF1-driven neurofibromas with annotated clinical data so that correlations can be delineated." (PMID 29987131, 2018). "LOH at the NF1 locus was detected in a subset of CALMs and neurofibromas, by either a gene conversion event or large deletion." (PMID 30302402, 2018). "The GI involvement occurs in 10–25% of patients with NF-1 presenting as solitary or multiple neurofibromas, leiomyomas, and rarely PNF." (PMID 29849532, 2018). "Superficial tumors resembling neurofibromas were noted in 40% (2/5) of the NF1 F0 animals and 37.5% (3/8) of the NF1 F1 minipigs by 4 months of age." (PMID 30302402, 2018). "Approximately 2/3rds of the patients had NF1 (43/74 MPNSTs, 7/9 atypical neurofibromas, and 21/21 plexiform neurofibromas)." (PMID 29796169, 2018). "Abdominal involvement in NF-1 occurs in the form of sporadic neurofibromas versus PNFs which can involve the liver, mesentery, retroperitoneum, and gastrointestinal (GI) tract." (PMID 29849532, 2018). "Aside from NF1 loss in specific cell populations (e.g. Schwann cells) an NF1 heterozygous microenvironment is critical for the formation of NF1 tumours like plexiform neurofibromas or optic gliomas." (PMID 29670214, 2018). "NF-1 has a variety of clinical manifestations: caft-au-lait macules, neurofibromas, freckling in the axillary or inguinal region, optic glioma, lisch nodules, osseous lesion, and PCC." (PMID 30613466, 2018). "Patient (Wu p001) was diagnosed as NF1 at the age of seven years by the presence of left craniofacial plexiform neurofibromas, infiltrative at the left temporal scalp, nodular subcutaneous tissue of the cheek, masticator space and probably the parotid space." (PMID 30290804, 2018). "The transcript levels of BRD4, EZH2 and TOP2A were determined in paired formalin-fixed paraffin-embedded (FFPE) neurofibroma/MPNST samples derived from the same NF1 patient and in a set of plexiform neurofibromas, atypical neurofibromas and MPNST." (PMID 28813519, 2017). "Extensive studies from human tissue analyses and mouse models have discovered that loss of heterogyzosity (LOH) of NF1 in Schwann cells and a heterozygous NF1 microenvironment are both important for the formation of neurofibromas." (PMID 29354122, 2017). "Our findings support the notion that neurofibroma SCs, some of which are Nf1−/−, promote a tumor microenvironment characterized by chronic inflammation, leading to altered gene expression in wild-type stromal cells, including macrophages." (PMID 28256556, 2017). "NF1 associated MPNST develop from benign precursors, so called neurofibromas, the hallmark of the disease." (PMID 29131833, 2017). "Loss of heterogyzosity of NF1 in Schwann cells and a heterozygous NF1 microenvironment are both important for the formation of neurofibromas." (PMID 29354122, 2017). "Herein, we report a rare case of NF-1 with bilateral plexiform neurofibromas arising from cervical vagus nerves." (PMID 28166752, 2017).
neurofibroma (continued). "Plexiform neurofibromas are strongly related to NF1, affecting 20% to 40% of patients suffering from this condition." (PMID 29179472, 2017). "There are several potential possibilities: 1) NF1 is known to encode a Ras-GTPase activating protein (Ras-GAP) and the Ras-MEK-ERK pathway is important for Nf1 neurofibroma formation." (PMID 26697518, 2015). "These neurofibroma types were studied using tissue-specific, biallelic, deletions of Nf1 in Nf1+/− mice." (PMID 26203125, 2015). "The role of steroid hormones in the NF1 phenotype has been discussed previously in the context of tumorigenesis as number and size of neurofibromas in NF1 individuals has been shown to increase during pregnancy and puberty." (PMID 25775093, 2015). "As malignancy develops, macrophages are recruited at higher densities to peripheral nerves and neurofibromas in mice and human beings when NF1 is inactivated in Schwann cells." (PMID 25759690, 2015). "Here, we describe the exome sequencing of breast cancer, MPNST, and neurofibroma from a patient with NF1." (PMID 26432421, 2015). "He stated that the tumors must arise along the course of a peripheral nerve or in a preexisting neurofibroma in patients with NF-1." (PMID 26114002, 2015). "Although neurofibromas are benign, a minority of patients with NF-1 show an increased incidence of malignancy such as MPNSTs, astrocytomas, and leukemias." (PMID 25317349, 2014). "Taking into consideration our NF1 sample, the number of neurofibromas ranged from 0 to 3,816 tumors, showing a tremendous variation." (PMID 25475340, 2014). "The most common tumor in individuals with NF-1 is the neurofibroma, a heterogeneous peripheral nerve sheath tumor." (PMID 25317349, 2014). "Plexiform neurofibromas are essentially pathognomonic for NF1 with diffuse involvement along a nerve segment or its branches, giving a “bag of worms” appearance." (PMID 25306531, 2014). "In contrast, when Nf1 is biallelically inactivated in Schwann cells and their precursors (Nf1 flox/flox; DhhCre), modeling grade 1 neurofibromas, Everolimus was ineffective at decreasing tumor volume." (PMID 24681606, 2014). "The dependence on these stromal cells and growth factors is nicely illustrated by Nf1 mouse models of plexiform neurofibroma and optic glioma." (PMID 25243094, 2014). "Biallelic NF1 inactivation is observed in neurofibromas and malignant peripheral nerve sheath tumors." (PMID 24137429, 2013). "We are aware of only four previous case reports on FMGCs in neurofibromas arising in the setting of NF1, as well as a recently published single retrospective clinicopathologic study of 22 patients with NF1 and FMGCs." (PMID 23890233, 2013). "Patients with NF-1 and plexiform neurofibromas have a higher mortality rate when compared with patients with or without asymptomatic plexiform neurofibromas." (PMID 23653673, 2013). "To comprehensively characterize the role of microRNAs in NF1 tumorigenesis, we analyzed 377 miRNAs expression in a large panel of dermal and plexiform neurofibromas, and MPNSTs." (PMID 23848554, 2013). "Comparison of 29 benign nerve sheath tumours (5 neurinomas, 24 neurofibromas) and 26 solid MPNST (3 sporadic and 23 NF1-associated MPNST) revealed a significantly higher methylation frequency in MPNST (p = 0.001, Pearson correlation)." (PMID 23139750, 2012). "If SKPs were the cells of origin of dermal neurofibromas, NF1−/− SKPs should be present within NF1 patient neurofibromas, although NF1+/− SKPs should also be detected." (PMID 22550514, 2012). "In a conditional plexiform neurofibroma mice model (NF1 flox/−; Krox20cre), haploinsufficient stromal and mast cells (NF1+/−) are necessary and limiting for neurofibroma development." (PMID 22550514, 2012). "Herein, we report two patients with a known history of NF1 presenting with multiple, extensive localized and plexiform neurofibromas." (PMID 23049566, 2012).
neurofibroma (continued). "Recently, we reported that haploinsufficiency of Nf1 in the hematopoietic microenvironment specifically has a critical role in plexiform neurofibroma formation." (PMID 21980365, 2011). "Our patient had classic NF-1, which is characterized predominately by neurofibromas of the peripheral nervous system." (PMID 21569290, 2011). "In NF1 families, a wide phenotypic and genotypic variability was evident, both in the spectrum of skin lesions (neurofibromas, café-au-lait macules) and in the type of visceral neoplasms." (PMID 21838856, 2011). "In the present study only 6 out of 518 neurofibromas (1.1%) belonged to NF1-microdeletion patients (N = 4)." (PMID 21031597, 2011). "Documented gastrointestinal manifestations of NF1 include neurofibromas, most commonly in the jejunum, ganglioneuromatosis leading to disordered gut motility, gangliocytic paragangliomas, periampullary duodenal carcinoid tumors and GISTs." (PMID 21838856, 2011). "Reviewing the literature, several clinic-based series of patients with NF1 have been reported, but only a few reports have specifically examined neurofibromas of the nipple-areolar complexes." (PMID 20205809, 2010). "Although multiple neurofibromas are characteristic of patients with NF-1, however, most cases of neurofibroma which are diagnosed in general are sporadic in nature." (PMID 15363097, 2004). "However, when compared to NF1 plexiform neurofibroma cell lines immortalized using the same methodology, the gene expression distances between primary cultures and immortalized cell lines were much smaller in magnitude than observed between the tumor types." (PMID 41564118, 2026). "Tax represses NF1 gene expression through suppression of the NF1 promoter, thereby allowing the development of neurofibromas without the need for direct mutations in the NF1 gene." (PMID 41153438, 2025). "Also, this vector demonstrated substantial transduction in an NF1−/− iPSC-derived neurofibroma xenograft (3MM), as shown by anti-GFP IHC." (PMID 41022755, 2025). "For NF1 microdeletion syndrome the hallmark is café-au-lait spots, freckling, neurofibromas, that were not present in our case." (PMID 41226044, 2025). "A total of 113 specimens were analysed, including 44 NF1-associated MPNSTs, 47 sporadic MPNSTs, 21 benign neurofibromas, and 1 non-neoplastic nerve sheath control." (PMID 40843672, 2025). "Although genetic testing was not performed, this case fulfilled the NF1 diagnostic criteria based on family history and the presence of neurofibromas and CALMs." (PMID 40051696, 2025). "NF-1 is an autosomal dominant neurocutaneous disorder characterized by skin abnormalities, such as café-au-lait macules and skinfold freckling, as well as peripheral nerve sheath tumors such as neurofibromas, schwannomas, and various other tumors." (PMID 40416267, 2025). "NF-1 is a complex multi-system neurocutaneous disorder with some of the common manifestations being café au lait macules, axillary/inguinal freckling, and neurofibromas." (PMID 41185817, 2025). "Hybrid neurofibroma/perineurioma tumors occur almost exclusively in NF1." (PMID 40218204, 2025). "Also, MPNST is reported to arise from benign plexiform neurofibroma and borderline atypical neurofibroma in the setting of NF1." (PMID 39789509, 2025). "Although no recurrent genetic alterations have been detected in benign neurofibromas, except for the NF1 gene variants, MPNST displays a diverse mutational spectrum including multiple gene mutations and DNA fragment deletions or duplications." (PMID 41463204, 2025). "This underscores the potential for these tumors to develop from pre-existing neurofibromas or nerve sheath elements even in patients without a germline NF1 mutation." (PMID 41328093, 2025).
neurofibroma (continued). "Overactivation of the Ras-like IA-PI3K-Rac2 pathway triggers the interaction between Nf1−/− Schwann cells and Nf1+/− mast cells, ultimately promoting the secretion of a type of protein that can remodel the ECM and promote angiogenesis, causing neurofibromas." (PMID 38651098, 2024). "In addition to GBM, RNF135 has been linked to increased risk of malignant peripheral nerve sheath tumors (MPNSTs) in neurofibroma patients with NF1 microdeletion." (PMID 39118262, 2024). "Intriguingly, isolated colonic neurofibromas that are not linked with NF1 or NF2 are extremely rare." (PMID 39070511, 2024). "Upon finding the germline NF1 variant, several years after presentation, a more detailed examination revealed 12 café-au-lait spots and axillary freckling but no neurofibromas." (PMID 38655100, 2024). "The same team used this iPSC-based NF1 (−/−) model to form neurofibroma tumors when engrafted in the sciatic nerve of nude mice, demonstrating the potential of this model to capture the genomic status of the initial tumors and their ability to retain their features." (PMID 38481529, 2024). "Additionally, upregulation of protumorigenic collagen expression in Nf1 neurofibroma fibroblasts has been recently discovered using single cell RNA sequencing." (PMID 38799507, 2024). "The presence of neurofibromas and café-au-lait spots confirmed the diagnosis of NF-1." (PMID 39726461, 2024). "In contrast, the hallmark clinical features of NF1 include Café-au-lait macules on the skin and the presence of multiple neurofibromas or plexiform neurofibromas, without the presence of schwannomas." (PMID 39157066, 2024). "The clinical features of Southern African patients with NF1 are similar to that of the known NF1 phenotype, with the exception of a lower frequency of plexiform neurofibromas and a higher frequency of developmental/intellectual disability compared to other cohorts." (PMID 38596211, 2024). "The approval and widespread availability of mitogen-activated protein kinase (MEK) inhibitors such as selumetinib for NF1-related plexiform neurofibromas have revolutionized the standard of care for patients with NF1, however their effective utilization hinges on early recognition of NF1." (PMID 39257551, 2024). "Treatment with MEK-inhibitors in adults with NF1-associated plexiform neurofibroma is uncommon, as they have not been approved by the European Medicines Agency (EMA) in this specific patient population." (PMID 38499890, 2024). "The neurofibromatosis-1 gene (NF1) was initially characterized because its germline mutation is responsible for an inherited syndromic disease predisposing tumor development, in particular neurofibromas but also various malignancies." (PMID 37627552, 2023). "A recent study of 135 NF1 patients with this mutation confirmed a lower frequency of LNs and the absence of spinal neurofibromas and symptomatic OPGs." (PMID 36831560, 2023). "While neurofibromas can develop in both NF1+/+ and NF1+/- microenvironments, a recent study found that a heterotypic population of differentiating NF1-/- Schwann cells and NF1+/- pNF-derived fibroblasts provided the most potent cell mixture for generating pNFs in vitro and in vivo." (PMID 37817770, 2023). "MEK inhibitors might have clinical efficacy in other NF1-associated tumors, given the role of the RAF/MEK/ERK pathway in neurofibromas." (PMID 37232809, 2023). "It is possible that the solitary round nodule seen on the Parthian kings’ imagery may be suggestive of a hereditary neurofibroma such as in NF1." (PMID 37908901, 2023).
neurofibroma (continued). "Based on previous studies and the current status of selumetinib, it is reasonable that NF1 related neurofibroma cells may alter the efficacy of selumetinib treatment by regulating the functional state of YAP." (PMID 36619222, 2023). "For symptomatic, inoperable symptomatic plexiform neurofibromas in patients with NF1 MEK inhibitors may be considered." (PMID 36684394, 2023). "Only children with NF1-related plexiform neurofibromas were included." (PMID 38560379, 2023). "In the MPNST microenvironment, an interesting finding is that the NF1+/− microenvironment may contribute to neurofibroma development." (PMID 36831419, 2023). "In April 2020, selumetinib, an oral selective MEK inhibitor that reduces PN size without serious adverse reactions in pediatric patients, was approved by the US Food and Drug Administration for the treatment of children with NF1-related progressive, inoperable plexiform neurofibroma." (PMID 37569527, 2023). "Of the four recognised genotype–phenotype correlations, missense variants affecting Arg1809 cause a NF1 phenotype similar to p.Met992del, demonstrating a lack of neurofibroma and frequency of LD similar to classical cohorts (50%)." (PMID 34897289, 2022). "Finally, in NF-1 cafe-au-lait macules, neurofibromas around the head and neck, optic glioma, lish nodules, osseous lesion, and PCh can be observed frequently." (PMID 35566714, 2022). "Some studies suggested that non-pathogenic MMR gene variants modify the number of neurofibromas in NF1 as they similarly act as a modifier in other diseases." (PMID 34997843, 2022). "Further, mosaic NF1 is confirmed if an identical first hit pathogenic NF1 variant is identified in two or more anatomically unrelated lesions such as CALM or neurofibromas in the absence of this pathogenic NF1 variant in unaffected tissue such as blood." (PMID 34928431, 2022). "Neurofibroma, a kind of nerve sheath tumor that may grow close to the spinal cord, peripheral nerves, or cranial nerves, is characteristic of NF1." (PMID 36090331, 2022). "Also, EGFR-dependent Nf1-/- SCPs show increased self-renewal and form neurofibromas upon transplantation." (PMID 35311647, 2022). "SCP-like cells increase in number in PNs; taken together with findings that Nf1–/– embryonic SCs show limited in vitro self-renewal capacity and form neurofibroma-like lesions in mice, we conclude that these are progenitor-like cells with roles in PN formation and/or growth." (PMID 36134665, 2022). "She had the NF1 microdeletion syndrome, characterized by a more severe phenotype, and presenting with variable facial dysmorphism, and clinical features, including a large number of neurofibromas for her age." (PMID 35456261, 2022). "In this study, we leveraged a common, naturally occurring NF1 missense mutation (c.5425C > T; p.Arg1809Cys) found in patients with NF1 who do not develop OPGs or neurofibromas." (PMID 35589737, 2022). "In contrast, mice with the Arg1809Cys Nf1 mutation, found in NF1 patients lacking neurofibromas or optic gliomas, do not exhibit neuronal hyperexcitability or develop these NF1-associated tumors." (PMID 35589737, 2022). "CDKN2A loss has also been observed to drive NF1 associated malignant transformation in neurofibromas, which may suggest an interaction between CDKN2A and NF1 in other tumor histologies as well that can potentially affect patient outcome." (PMID 36380219, 2022). "While the P2ry14 inhibitor (PPTN) has poor PK properties, when drug candidates targeting P2ry14 become available, they may be useful for prevention or treatment of NF1-driven neurofibromas." (PMID 35311647, 2022). "No freckling or neurofibroma was found in three probands, and no NF1 or SPRED1 mutation was detected by genetic analysis." (PMID 36438053, 2022). "Loss-of-function mutations in both NF1 alleles are detected in neurofibroma SCs but not in other neurofibroma cell types." (PMID 36134665, 2022).